CXCL16 (C-X-C motif chemokine ligand 16)
Diseases named in the same sentence as CXCL16 in open-access papers (continued):
Sharing a sentence is not in itself a finding about the gene and the disease.
tumor (continued). "Furthermore, simvastatin increased CXCL16 expression in LSECs, while CXCL16 remains a ligand for the CXCR6 receptor expressed by NK cells, causing the recruitment of natural killer (NK) cells and leading to an anti-tumor immune-mediating response." (PMID 39408564, 2024). "While it is challenging to definitively attribute an anti-tumor role to CXCL16-expressing NK cells, they may contribute to the activation of CXCR6+ immune cells, such as invariant NKT cells and intratumoral CD8+ T cells, potentially enhancing their anti-tumor capacity." (PMID 39409924, 2024). "Indeed, CXCL16 and CCL5 have already been shown to be associated with increased activity and infiltration of T cells and NK cells to different sites, further supporting the notion that these molecules directly affect anti-tumor immunity." (PMID 36646904, 2023). "However, the role of CXCL16 in cancer is complex, as transmembrane CXCL16 may promote antitumor responses, whereas soluble CXCL16 may contribute to tumor progression." (PMID 35320940, 2022). "Additionally, Th1 cell-derived IFN-γ induces enhanced production of tumorotoxic nitric oxide and TNF-α in tumor-infiltrated macrophages while Th17 cell-sourced IL-17 stimulate production of CXCL16 in tumor DCs, enabling increased recruitment of tumoricidal CCR6-expressing CD8+CTLs." (PMID 35757015, 2022). "In addition, expression of CXCL16 inversely correlated with tumor stage, the invasion depth of the tumor and lymphatic invasion, what may suggest that this chemokine and its receptor CXCR6 may play a role in gastric tumorigenesis." (PMID 33182840, 2020). "Although no reports have been published on the effect of carbon ion irradiation on chemokine secretion, a previous report demonstrated that X-ray irradiation to a tumor strongly induced CXCL16, which may lead to increased recruitment of T cells at the distant site." (PMID 30774761, 2019). "Indeed, CXCR6 and CXCL16 are upregulated in multiple cancer tissues, including primary and metastatic tissues, and cancer cell lines compared to respective normal ones and their levels increase as tumor malignancy progresses." (PMID 31698786, 2019). "Increased plasma CXCL16 levels may promote tumor angiogenesis in the first month after MICR." (PMID 29981574, 2018). "Furthermore, CXCL16/CXCR6 interaction was required for full NK T cell and dendritic cell activation and maturation, and also mediated the adhesion of cytotoxic T cells to tumor-associated macrophages (TAM)." (PMID 28267793, 2017). "Therefore, although CXCR6/CXCL16 interactions enhance beneficial IFNγ responses from iNKT cells, there could be additional mediators or processes regulated by CXCR6/CXCL16 interactions that contribute to tumor control." (PMID 27471636, 2016). "However, only a fraction of the TN tumours expressed CXCL16 in the fibroblasts." (PMID 27725631, 2016). "At the same time, based on Ezrin phosphorylation observed in response to CXCL16 in PC3, it could be inferred that CXCR6-CXCL16 interaction may cause cytoskeleton rearrangement and promote tumor cell metastasis independent of androgen." (PMID 26799186, 2016). "Although CXCL16 methylation was detected in adjacent normal renal tissue from RCC patients with tumour methylation, this might indicate a premalignant field defect (as described in bronchial epithelium); however, contamination by tumour cells cannot be excluded completely." (PMID 18195710, 2008). "Within the tumor microenvironment, gene expression profiling revealed upregulated chemokine signaling pathways (CCR2/CCL7, CXCR6/CXCL16) and key immunosuppressive markers, including PD-L1 and TGF-β1." (PMID 42227811, 2026). "BAs also play an important role in immunosurveillance of tumor growth in the liver, where the balance between primary and secondary BAs is fundamental for NKT cell accumulation mediated by the CXCR6/CXCL16 axis." (PMID 39851512, 2025).
tumor (continued). "The activation of NKT cell enrichment depends on the bile duct conversion in a C-X-C motif chemokine ligand 16 (CXCL16) manner, so the aberrant microbiome translocation in the gut will diminish NKT cell accumulation, thus impeding anti-tumor effects." (PMID 39921821, 2025). "We found that CXCL16 recruited and activated CD8+ T cells, especially GZMA+CD8+ T cells, a subpopulation of CD8+ T cells that has potent cytotoxicity to tumor cells." (PMID 40924501, 2025). "Single-cell and spatial transcriptomics revealed that ZEB1 ablation promoted tumor pyroptosis by recruiting and activating GZMA+CD8+ T cells in the tumor core through epigenetic upregulation of CXCL16." (PMID 40924501, 2025). "CXCL16 combines with the chemokine CCL20 to engage innate and adaptive immune cells that participate in tumour immune initiation and response stages, enhance the overall antitumour immune response, and enhance therapeutic efficacy." (PMID 40792261, 2025). "Some studies have shown that tumor cells can secrete CXCL16 to recruit immune cells expressing CXCR6, such as NK cells and CD8+ T cells, to the tumor site, which can directly kill tumor cells." (PMID 40539058, 2025). "The enhancement of tumor cell recognition and CD8+ T cell activation in OT-1 T cells suggested a direct response to CXCL16 stimulation." (PMID 40924501, 2025). "Cxcl14, a CXCR4-inhibitory ligand, localized to the outer tumor margins, whereas Cxcl16, a CXCR6 ligand important for effector T cells and ILC2s, was enriched in the tumor core." (PMID 40630529, 2025). "Nevertheless, while CCL5 became a more dominant ligand for CCR5 in the KPC-4545 tumor, CCL4 remained a dominant ligand for CCR5 and CXCL12, CXCL10, and CXCL16 arose as major ligands for different receptors in the KPC-3403 model following anti-IL-1β treatment." (PMID 39948655, 2025). "In this model, YAP1 upregulation suppressed CXCL16-driven CD4+/CD8+ TIL recruitment and increased MMP7 expression, resulting in elevated RCB scores and reduced tumor remission." (PMID 40731926, 2025). "The expanded NK cells express the chemokine receptors CXCR3, CCR5, and CXCR6, and the lung of tumor-resected mice express mRNA of the corresponding ligands CXCL9/10/11, CCL3/4/5, and CXCL16." (PMID 39835538, 2025). "These glyCAFs produce the C-X-C motif chemokine ligand 16 (CXCL16), which traps cytotoxic CD8+ T cells at the tumor margins, restricting their infiltration and promoting an immunosuppressive environment." (PMID 40940809, 2025). "The level of CDCA has been reported to correlate with liver sinusoidal endothelial cell CXCL16 mRNA expression, which can promote CXCR6 + hepatic nature killer T (NKT) cell recruitment to the liver and inhibit liver tumor growth in a tumor metastasis model." (PMID 39804065, 2025). "Primary BAs such as CDCA and toxic CA increase CXCL16 expression, which binds to its receptor CXCR6 on NKT, thereby increasing IFN gamma production and inhibiting tumor growth." (PMID 39064815, 2024). "While BKCa and CXCL16 promote the aggregation and activation of αVβ3, thus trigger the activation of downstream FAK to enhance tumor cell migration and invasion abilities." (PMID 38385080, 2024). "Considering the spatial positioning of CXCL16-expressing cells and their impact on the CXCR6+ T cells within the tumor microenvironment is crucial." (PMID 38509063, 2024). "Conversely, CXCL16 exerted pro-tumorigenic effects in BCa by activating the ERK1/ERK2 signaling pathway and promoting tumor proliferation in response to IFNγ." (PMID 39409924, 2024). "Pre-treatment with oxaliplatin and cyclophosphamide induced a pro-inflammatory tumor microenvironment and enhanced secretion of CCL5, CXCL9, CXCL10, and CXCL16 by tumor-infiltrating macrophages, leading to enhanced ROR1-CAR-T cell infiltration." (PMID 36949946, 2023). "The C3-1-TAg TNBC primary tumor-bearing mice were primed with MCT for two weeks and then treated with anti-PD-1 antibody in combination with either IgG or CXCL16 NAb." (PMID 37055410, 2023).
tumor (continued). "Taken together, these findings suggest that following gemcitabine therapy, MEPs directly affect CD8 + T cells and NK cells probably via the secretion of CXCL16 and CCL5, thereby contributing to anti-tumor immunity." (PMID 36646904, 2023). "Upon binding to CXCR6 on hypoxic CA-MSCs, CXCL16 promotes the expression of CXCL10, resulting in further MSC recruitment to the tumor site due to more CXCL16 expression." (PMID 38022534, 2023). "On the other hand, an important study pointed out that CXCR6, the receptor for CXCL16, plays a key role in CTL-mediated tumor control, and contributes to the survival and local expansion of effector-like CTL in the TME." (PMID 36966334, 2023). "This chemokine receptor can position CD8+ cytotoxic T lymphocytes (CTL) in perivascular niches in the tumor stroma, which is enriched in DC3 (CCR7+ DC) expressing the ligand of CXCR6, CXCL16." (PMID 37545498, 2023). "We observed a moderate positive correlation for CXCL5, CXCL16, as well as CEA and CA 19–9 with tumor TNM stage." (PMID 37848726, 2023). "Expression of chemokine receptors that match ligands secreted by the tumor such as CCL2, CCL22, CXCL16, CX3CL1, CXCL1 and CXCL8 can enable CD8+ T cells to enter the tumor." (PMID 37301772, 2023). "Other studies have shown that tumor cells that interact with MSC via ligand receptors include SDF-1, VEGF, TNF-α, PDGF, and CXCL16." (PMID 36966336, 2023). "This is a high number compared to the ectopically expressed chemokines CXCL16 and CXCL17 that were previously shown to stain 5 and 17% of the tumor cells in primary CC tumors." (PMID 38156105, 2023). "Among the identified MEP-secreted factors we note the presence of CXCL16 and CCL5, which are known to activate anti-tumor immune cells such as CD8 + T cells and NK cells in different tumor models." (PMID 36646904, 2023). "In primary tumors, PCa-derived CXCL16 recruits CXCR6-expressing MSCs which upregulate PCa CXCR4 expression, induce EMT markers via CXCL12 secretion, and promote tumor growth in vivo in a subcutaneous model." (PMID 37025604, 2023). "M1 macrophages exhibit enhanced antigen-presenting activity while secreting CXCR3 ligands (CXCL9, CXCL10, CXCL11) and CXCL16 to recruit Th1 and NK cells and secrete TNF-α, synergistically exerting anti-tumor functions." (PMID 37063892, 2023). "The study has shown that increased IL-18 production induced C-X-C Motif Chemokine Ligand 16 (CXCL16) secretion, which recruited immunosuppressive bone MDSCs and enhanced tumor cell proliferation and migration." (PMID 37833958, 2023). "Next, we designed a sequential treatment regimen of CXCL16 NAb and STAT1 inhibitor to test possible enhanced efficacy of sensitizing MCT-primed tumor to anti-PD-1 treatment." (PMID 37055410, 2023). "Radiation therapy plays a role in promoting the migration of effector T lymphocytes to the tumor site by inducing the expression and release of chemokines, such as CXCL-10 and CXCL-16, from tumor cells." (PMID 37511431, 2023). "We further demonstrated that these effects are attributed, at least in part, to the increased expression of CXCL16 and CCL5 by MEPs, which in turn support the anti-tumor activity of CD8 + T cells and NK cells." (PMID 36646904, 2023). "Radiotherapy is demonstrated to induce the expression of CXCL16, one of the proinflammatory cytokines that enhances the chemotaxis of CTL cells into the tumor bed and increases their ability to execute anti-tumor cytotoxicity." (PMID 35053449, 2022). "Lysates of MTX-treated 9464D tumors displayed a more than 2.5-fold increase of IL1a, CXCL16, FLT3L, CX3CL1 and IL1RA, and a more than 1.5-fold increase of CXCL10, CXCL5, CCL5 and CXCL9 compared to control tumor lysates." (PMID 36397148, 2022). "The capacity of MSCs to move toward tumor tissue is also mediated by other factors, such as chemokines CCL2, CCL5, CXCL16, diffusible cytokine IL-8, as well as growth factors IGF1, PDGF, VEGF, and TGF-β." (PMID 36324128, 2022).
tumor (continued). "The CXCL16 immunohistochemical analysis of 58 colorectal samples, collected during surgery, demonstrated a higher CD4 and CD8 tumor infiltration in patients who exhibited a high level of this chemokine expression." (PMID 36429101, 2022). "Several previous studies and reviews highlighted the up-regulation of CXCL16 and/or CXCR6 by tumor cells and their role in tumor growth, migration and invasiveness." (PMID 36311728, 2022). "CXCL16, the chemokine ligand of CXCR6, was detected in supernatants from the majority of dissociated tumour and GNS cell samples." (PMID 35464424, 2022). "The levels of CXCL16 and CXCR6 are detected in various cancers and correlated with both better and worse survival, dependent on tumor types." (PMID 35959371, 2022). "As CXCL16 is the ligand for CXCR6 which is expressed mostly on NKT cells, the cell frequencies of CXCR6+ NKT cell in tumor tissues of various groups were evaluated by flow cytometry." (PMID 34983554, 2022). "Further animal experiments determined that OCA combined with 5β-CA was highly effective in upregulating CXCL16 production, thereby increasing the hepatic number of NKT cells and exerting a significant tumor growth–inhibition effect." (PMID 36605219, 2022). "Significantly increased concentration of CXCL16, IL-27, IFN-γ, and IL-17 and decreased concentration of immunosuppressive TGF-β and IL-10 were measured in serum samples and tumor tissues of 4T1+d-MAPPS-treated mice." (PMID 35757015, 2022). "Lysate from MTP-treated tumors showed an even stronger upregulation of chemokines involved in immune cell recruitment, including CXCL9, CCL5, CXCL10, CD40 and CXCL16, compared to both control and MTX-treated tumor lysates." (PMID 36397148, 2022). "The explanation for the observed improvement is most likely that GPR55 is a marker for T cells and B cells in lymph nodes, whereas CEA, CXCL16 and CXCL17, are markers for tumor cells of epithelial origin." (PMID 35562947, 2022). "have found that CXCL16-positive DCs can enhance iNKT cell-dependent IFN-γ production and tumor control." (PMID 35320940, 2022). "Bone-homing tumor cells tend to overexpress chemokine receptors, CXCR4, CXCR6, and CXCR2 that subsequently contribute to the movement of the tumor cells from the bone marrow to other organs by seeking CXCL12, CXCL-16, and CXCL-10 respectively." (PMID 35399952, 2022). "ORFV infection induces tumor cell apoptosis that facilitates phagocytosis of dying tumor cells by DCs and recruits CD8 T cells through the CXCL16/CXCR6 axis." (PMID 35959371, 2022). "At day 25, we surgically removed the primary tumor and performed TCR-β repertoire sequencing to characterize the difference in T cell infiltration in the pre-metastatic lung tissue following CXCL16 antibody blocking." (PMID 33979626, 2021). "As a chemokine, the binding of CXCL16 to its sole receptor CXCR6 can involve biological activities such as cell adhesion and anti-tumor immunity." (PMID 34676171, 2021). "It has also been demonstrated that CXCL16/CXCR6 signaling acts directly on the primary GBM cells, promoting tumor cell growth, migration, and invasion." (PMID 34071306, 2021). "MSCs promptly migrate into tumor sites in response to chemokines, such as CCL2, CCL5, CXCL12, and CXCL16, and are expanded by cytokines, such as TGFβ, VEGF, FGF, and IGF, all of which are released from the tumor milieu." (PMID 33535613, 2021). "Cancer patients with high levels of CXCL16 expression have shown more elevated levels of CD4(+) and CD8(+) tumor-infiltrating lymphocytes and NK, leading to improved disease prognosis." (PMID 34150764, 2021). "The mutual binding of CXCL16 and CXCR6 involves a variety of biological activities, including cell adhesion and anti-tumor immunity." (PMID 34676171, 2021). "(ii) RT also regulates the tumor microenvironment, increases the levels of chemokines CXCL10 and CXCL16 in the tumor microenvironment, and promotes the migration of CD8+T cells to the tumor site." (PMID 33465302, 2021).
tumor (continued). "CXCR6 functions as the receptor of CXCL16, and the CXCL16/CXCR6 signaling system is involved in the progression of tumor growth." (PMID 34722241, 2021). "CXCL16 is the ligand of CXCL6, and CXCR6 upregulation is critical for continuous tumor control mediated by CD8+ cytotoxic T cells." (PMID 35127816, 2021). "Measurements of CXCL16 and CXCL17 strengthen the prognostic value of LGR5 by detecting high number of aggressive tumor cells and/or tumor growth promoting cells in the tumor cell microenvironment." (PMID 35008827, 2021). "For instance, CAF‐secreted chemokines like CCL7 and CXCL16 strongly induced the activation of TGF‐β pathway in HCC, which significantly accelerated tumour metastasis." (PMID 33713546, 2021). "Bile acids can influence production by liver sinusoidal endothelial cells of the CXCL16, which recruits natural killer T (NKT) cells to the tumour, inhibiting primary and metastatic tumour growth." (PMID 33213502, 2020). "Tumor cells release multiple chemokines after receiving radiation, including CXCL9, CXCL10, and CXCL16, and these chemokines can recruit activated T cells to tumors." (PMID 32992835, 2020). "Oral administration of vancomycin altered gut commensal bacteria in mice, increasing CXCL16 expression of liver sinusoidal endothelial cells, thus recruiting hepatic CXCR6+ NKT cells that exert anti-tumor effect." (PMID 31991677, 2020). "Tumor cell-conditioned myeloid suppressor cells were shown to produce CCL2 and CXCL16, which enhanced angiogenesis." (PMID 31527616, 2019). "The correlations between the mRNA expression levels of CXCL14, CXCL16, and CXCL17 in the primary tumor tissues were assessed by a two-tailed Spearman’s rank order correlation test." (PMID 31752131, 2019). "MSCs are recruited to and persist in tumors in several models of primary cancers due to the secretion of tumor-derived chemoattractants such as CXCL12, CXCL16, LL37, and cyclophilin B." (PMID 29642534, 2018). "In vitro, the chemokines increased after radiotherapy in the parental tumor cell, and CCL2-5, CXCL9, CXCL10, CXCL16 were much higher than in the resistant cell." (PMID 30093664, 2018). "Thus, based on the prior literature, CXCL16 may hold some promise as a tumor marker." (PMID 29981574, 2018). "Another study on hepatocellular carcinoma indicated importance of CXCL16 and its receptor CXCR6 in neutrophil recruitment and tumor progression due to its ability to stimulate the release of CXCL8 by tumor cells." (PMID 29340117, 2017). "Considering chemotactic factors, the mRNA expression of CCL5, CXCL9, CXCL16, and CCL25 was higher in HCCLM3 cells from micrometastatic regions than in cells from primary tumor sites when cocultured with MSCs." (PMID 28205428, 2017). "RT can also facilitate the recruitment of effector T-cells to the tumor by inducing the secretion of CXC motif chemokine ligand CXCL9, CXCL10 and CXCL16 by tumor cells." (PMID 29100279, 2017). "Chemokines in the omental tumor tissues revealed some changes as follows: 1) the decreased levels in CCL26, CCL28, CXCL1-3, CXCL8 and CXCL16; 2) the increased level in CCL24; and 3) the conserved level in CCL20 compared to the parental cells." (PMID 27723802, 2016). "Recent study on hepatocellular carcinoma indicated importance of CXCL16 and its receptor CXCR6 in neutrophil recruitment and tumor progression, due to its ability to stimulate tumor cells to release CXCL8." (PMID 26648665, 2015). "This is illustrated by experiments in a poorly immunogenic mouse carcinoma, in which ionizing radiation induced upregulation of chemokine CXCL16, which recruited effector CD8+ T cells to the tumor." (PMID 25622640, 2015). "Our group demonstrated in a poorly immunogenic mouse carcinoma that radiation-induced up-regulation of the chemokine CXCL16 was required for the efficient recruitment to the tumor of CXCR6+ effector CD8 T cells, resulting in optimal tumor inhibition." (PMID 22937524, 2012).